PPIL3 (peptidylprolyl isomerase like 3)
Description:
PPIases accelerate the folding of proteins. It catalyzes the cis-trans isomerization of proline imidic peptide bonds in oligopeptides. May be involved in pre-mRNA splicing.
Synonyms: CyPJ
Tractability: Small molecule: a structure with a bound ligand is known. PROTAC: ubiquitination databases record sites on it; its protein half-life has been measured.
Gene: Protein-coding gene on chromosome 2 (200,870,907 to 200,889,353, reverse strand). Ensembl gene ENSG00000240344.
Subcellular location (Human Protein Atlas): Nucleoplasm; Nucleoli
Pathways (Reactome):
Disease: Dengue Virus-Host Interactions
Metabolism of RNA: mRNA Splicing - Major Pathway
Gene Ontology:
Molecular function: protein binding; peptidyl-prolyl cis-trans isomerase activity
Biological process: mRNA splicing, via spliceosome; protein folding
Cellular component: catalytic step 2 spliceosome; nucleoplasm
Genetic constraint (gnomAD): Loss-of-function variants: 4 observed, 5.26 expected, observed/expected ratio (o/e) 0.76, 90% interval 0.37 to 1.64. That is too few expected variants to judge how well the gene tolerates losing a copy. Missense variants: 62 observed, 80.35 expected, observed/expected ratio (o/e) 0.77, 90% interval 0.63 to 0.95. Synonymous variants: 36 observed, 29.56 expected, observed/expected ratio (o/e) 1.22, 90% interval 0.93 to 1.61.
Homologues: Orthologues: dog PPIL3 (100% identical), pig PPIL3 (100% identical), rabbit PPIL3 (100% identical), chimpanzee PPIL3 (99% identical), mouse Ppil3 (98% identical), guinea pig PPIL3 (97% identical), tropical clawed frog ppil3 (86% identical), Caenorhabditis elegans cyn-10 (70% identical). Paralogues in human: PPIL2 (51% identical), PPWD1 (51% identical), PPID (45% identical), PPIG (44% identical), PPIL1 (44% identical), CWC27 (43% identical), PPIC (43% identical), NKTR (43% identical), PPIA (43% identical), PPIF (42% identical), PPIB (41% identical), PPIAL4C (40% identical), and 10 more.
Diseases named in the same sentence as PPIL3 in open-access papers:
PPIL3 is named in the same sentence as 18 diseases in open-access papers, as found by Europe PMC text mining. Sharing a sentence is not in itself a finding about the gene and the disease. The quoted sentences say what the papers report.
glioma (2 papers, 2015 to 2018). A benign or malignant brain and spinal cord tumor that arises from glial cells (astrocytes, oligodendrocytes, ependymal cells). "Cyclophilin J has also been cloned by another laboratory under the name of PPIL3 (Peptide-Prolyl Isomerase-Like 3), and its upregulation in human glioma was reported." (PMID 26020957, 2015).
breast carcinoma (1 paper, 2025). "Studies have revealed that the expression of PPIL3 is significantly connected with OS of breast cancer." (PMID 40642086, 2025).
melanoma (1 paper, 2024). A malignant, usually aggressive tumor composed of atypical, neoplastic melanocytes. "Genes in cluster 8 (GSTO2, LRRC34), 9 (CLPTM1L) and 10 (CTSS, SETDB1, ANXA9, GOLPH3L, HORMAD1, PPIL3, CASP9, ALS2CR12) underlie the association between melanoma and cancers." (PMID 38308491, 2024).
schizophrenia (1 paper, 2025). A major psychotic disorder characterized by abnormalities in the perception or expression of reality. "Using an integrative approach combining bulk transcriptomics, snRNA-seq, and an MK-801 mouse model, we observed reduced OXPHOS in schizophrenia and identified three candidate genes—MALAT1, PPIL3, and ITM2A—associated with this process." (PMID 41199749, 2025). "To probe its molecular basis in schizophrenia, we applied complementary methodologies with multi-level validation, which converged on three genes—MALAT1, PPIL3, and ITM2A—that consistently correlated with OXPHOS activity." (PMID 41199749, 2025). "ROC analysis showed that five genes—MALAT1, PPIL3, ITM2A, MTA2, and GJA1—effectively distinguished schizophrenia from controls (AUC >0.70)." (PMID 41199749, 2025). "Correlation analysis linked OXPHOS scores positively with PPIL3 and ITM2A, negatively with MALAT1 and GJA1, and not significantly with MTA2, suggesting their role in schizophrenia-related mitochondrial dysfunction." (PMID 41199749, 2025).
cancer (9 papers, 2015 to 2025). A tumor composed of atypical neoplastic, often pleomorphic cells that invade other tissues. "Notably, PPIL3 expression was lower in cancer tissues for both patient groups." (PMID 40642086, 2025). "In addition, we evaluated whether PPIA, PPIB or PPIL3 could be correlated with cisplatin sensitivity in liver tissue-derived cancer cell lines." (PMID 36230472, 2022). "Patients who did not respond to immunotherapy had cancer tissues with elevated BMP6 and FN1 expression, in contrast to those who responded, where CD274, HOXB5, and PPIL3 were more expressed." (PMID 40642086, 2025).
tumor (6 papers, 2015 to 2025). "In summary, we believed that PPIL3 inhibits Bca cell proliferation and promotes the formation of an anti-tumor immune microenvironment by inducing senescence." (PMID 40642086, 2025). "In vitro experiments showed elevated expression of PPIL3 facilitated the concentration of senescence markers (SA-β-gal) and inhabited tumor cell proliferation." (PMID 40642086, 2025). "Immunohistochemical staining of consecutive FFPE tumor sections from PTC patients demonstrated co-expression of the CLIP2 and PPIL3 proteins." (PMID 32727620, 2020).
PPIL3 also shares sentences with these, for which no sentence is quoted: hepatocellular carcinoma (3 papers); colitis (2); liver cancer (2); bladder cancer (1); colon carcinoma (1); colorectal cancer (1); gastric adenocarcinoma (1); immune complex diseases (1); ovarian carcinoma (1); papillary thyroid carcinoma (1); rheumatoid arthritis (1); transitional cell carcinoma (1).